IL22 (interleukin 22)
Diseases named in the same sentence as IL22 in open-access papers (continued):
Sharing a sentence is not in itself a finding about the gene and the disease.
atherosclerosis (continued). "To date, the contribution to atherosclerosis has been addressed for IL-10, IL-19, and IL-22." (PMID 33562334, 2021). "Although many studies have demonstrated the beneficial effects of decreased expression, it is currently difficult to speculate on the most effective method to inhibit IL-22 expression in atherosclerosis." (PMID 34388961, 2021). "Taken together, these data suggest that the IL-1β/ IL-1R1/IL-22 axis may play a key role in the aetiology of atherosclerosis." (PMID 34388961, 2021). "The crosstalk of IL-22 and innate and adaptive immunity in atherosclerosis is worthy of attention." (PMID 34388961, 2021). "Moreover, in another study of atherosclerosis, IL-22R1 and IL-22 are expressed in mouse atherosclerotic plaques, and their expression levels are significantly elevated in apoE knockout mice." (PMID 34388961, 2021). "The role of IL-22 in atherosclerosis has been addressed in a few recent studies." (PMID 33562334, 2021). "Thus, further studies are needed to explore the exact mechanism by which IL-38 regulates IL-22 expression and production in atherosclerosis." (PMID 34388961, 2021). "IL-22 promotes the development of atherosclerosis by multiple mechanisms, which may be a promising therapeutic target in the pathogenesis of atherosclerosis." (PMID 34388961, 2021). "Thus, it is necessary to explore which immune cells-derived IL-22 affects these atherosclerosis-related immune cells." (PMID 34388961, 2021). "A recent study reported that deficiency of IL-23 significantly decreased IL-22 expression in ApoE-knockout mice, and also reduced expression of IL-22, thereby relieving the release of inflammatory substances, and thus alleviating the process of atherosclerosis." (PMID 32194399, 2020). "However, further in vitro study established the protective role of IL-22 against endothelial dysfunction, an essential process involved in the early development of atherosclerosis and vascular complications in T2DM." (PMID 27829708, 2016). "To determine their roles in the pathogenesis of atherosclerosis, we examined the frequencies of Th22 cells and levels of plasma IL-22 in peripheral blood of AMI, UA and SA patients, and assayed their correlations with the related clinical parameters in this study." (PMID 24312440, 2013). "The proinflammatory effects of Th22 in the development of atherosclerosis may be dependent on the synergistical effects of IL-22 and TNF-α, which are the main effective cytokines of Th22 cells." (PMID 24312440, 2013). "There were some studies that initially revealed the role of Th22/IL-22 in atherosclerosis." (PMID 24453425, 2013). "The function of IL-22 in atherosclerosis is largely unknown, although evidence suggests that IL-22 is involved in vascular remodeling by promoting pro-inflammatory chemokines and antimicrobial peptide secretion as well as increasing VSMC migration and proliferation." (PMID 35600479, 2022). "Also, increasing evidence suggests that IL-22 may promote atherosclerosis through multiple mechanisms by these effector cells." (PMID 34388961, 2021). "Thus our results further indicate that Th17 cells in the local inflammation environment of atherosclerosis could develop into IL-22 producing Th17 cells." (PMID 24312440, 2013). "IL-22 may be involved in atherosclerosis by the JAK/STAT pathway and MAPK pathways." (PMID 24453425, 2013). "Th22 cells express IL-22 and have been found at increased levels in subjects with ACS, aggravating atherosclerosis on an ApoE−/− mice model further on by inducing Th17 proliferation." (PMID 37600028, 2023). "Also, IL-22 may be regulated by other cytokines and proteins during atherosclerosis." (PMID 34388961, 2021). "Thus, upregulation of IL-25 may alleviate atherosclerosis by reducing IL-22 expression." (PMID 34388961, 2021). "Thus, these cells may be the main target for IL-22 in atherosclerosis." (PMID 34388961, 2021).
atherosclerosis (continued). "The results of dynamic analyses showed that Th22 cells, which secrete the majority of IL‐22 among the known CD4+ cells, play a major role in atherosclerosis." (PMID 32022386, 2020). "IL-22 expression has also been confirmed in a variety of inflammatory cell types, including macrophages and T cells, as well as in vascular smooth muscle cells (VSMC), further indicating a role in atherosclerosis." (PMID 37047399, 2023). "Collectively, IL-22 acts as an important cytokine in the regulation of VSMC proliferation and migration and may be a promising therapeutic target for atherosclerosis." (PMID 34388961, 2021). "Moreover, to check whether Th17 cells could develop into IL-22 producing Th17 cells in the local inflammation environment of atherosclerosis, we analyzed CD4+IFN-γ−IL-17+IL-22+ cells separately." (PMID 24312440, 2013).
chronic mucocutaneous candidiasis (23 papers, 2010 to 2025). "The most significant observations refer to the appearance of autoantibodies to IL-17 or IL-22 and increase susceptibility to chronic mucocutaneous candidiasis (CMC), as these cytokines have a major role in protecting against CMC." (PMID 29651292, 2018). "This paradigm is likely applicable to other susceptible hosts, such as patients with chronic mucocutaneous candidiasis who exhibit reduced production of IL-17 and IL-22." (PMID 25344377, 2014). "IL-22 and IL-17 are crucial natural defense mechanisms against chronic mucocutaneous candidiasis (CMC)." (PMID 39195286, 2024). "The effect of IL-22 in defensing against fungi has been reported in pulmonary Aspergillus fumigatus infection in lungs and Chronic Mucocutaneous Candidiasis." (PMID 35432360, 2022). "Chronic mucocutaneous candidiasis (CMC) is associated with anti-interleukin (IL)-17A, anti-IL-17F, or anti-IL-22 autoantibodies." (PMID 31892200, 2019). "Besides, APECED is characterized by high-titer antibodies against a wide variety of cytokines that could partly be responsible for the clinical symptoms during APECED, mainly chronic mucocutaneous candidiasis, and linked to antibodies against Th17 cells effector molecules, IL-17 and IL-22." (PMID 22876245, 2012). "In particular, patients with disseminated Talaromyces marneffei infection or histoplasmosis should be screened for AIGAs, patients with Cryptococcus gattii infection for anti-GM-CSF antibodies, and patients with chronic mucocutaneous candidiasis for anti-IL-17A/F (IL-22), where possible." (PMID 37623553, 2023). "Interestingly, neutralizing autoantibodies against Th17 cell cytokines IL-17A, IL-17F, and IL-22 have been reported in chronic mucocutaneous candidiasis (CMC) patients with autoimmune polyendocrinopathy syndrome-1 (APS-1) or thymoma." (PMID 21079687, 2010). "IL-22 along with IL-17F is a vital natural defender against Chronic Mucocutaneous Candidiasis (CMC)." (PMID 33042126, 2020). "The role of ACAAs has most extensively been studied in patients with chronic mucocutaneous candidiasis (CMC) where auto-antibodies against IL-17 and IL-22 play a role." (PMID 38203686, 2023). "Chronic mucocutaneous candidiasis (CMC) has been observed in individuals with anti-IL-17A, anti-IL-17F, and anti-IL-22 autoantibodies, resulting from these autoantibodies blocking the Th-17 immunity." (PMID 35003106, 2021). "Both autoimmune polyendocrinopathy‐candidiasis‐ectodermal dystrophy (APECED) and the rare thymoma patients with chronic mucocutaneous candidiasis (CMC) have neutralizing autoantibodies to Th17 cytokines and significant defects in production of IL‐22 and IL‐17F by their T cells." (PMID 27957331, 2016).
Salmonella Infections (23 papers, 2012 to 2025). Infections with bacteria of the genus SALMONELLA. "That's why prompt up-regulation of IL-22 by dendritic cells is seen at site of Salmonella infection to cause resistance against salmonellosis." (PMID 33042126, 2020). "It has been reported that IL-17 and its associated cytokines (IL-21 and IL-22) are induced in the gastrointestinal tract during Salmonella infection." (PMID 27891321, 2016). "At 9 dpi, IL-17A and IL-22 transcription in response to Salmonella infection were significantly elevated in TCR Cγ−/− compared to wild-type chickens." (PMID 40438105, 2025). "In fact, increased IL-22 promotes Salmonella infection by improving its ability to compete with microbiota." (PMID 37483638, 2023). "In this context, upregulation of S100a9 and Reg3g as well as elevated IL-22 serum levels during Salmonella infection suggesting alternative signaling pathways potentially mediated via STAT348." (PMID 34497340, 2022). "It seems that Salmonella vaccines are able to induce the production of circulating of IL-22 that has been shown to play an important role in protecting the gut tissue integrity and enhance disease lessening through chronic Salmonella Infection." (PMID 36466847, 2022). "To determine the influence of SFB on the rapid CD4+ T cell response during Salmonella infection, specifically IL-22 production, we cohoused eSPF reporter mice with SFB monocolonized donor mice for 14 days." (PMID 34566952, 2021). "Strikingly, mice from this eSPF barrier almost completely lost their ability to induce innate IL-17A and IL-22 producing CD4+ T cells upon Salmonella infection and cytokine production ability was successfully restored upon colonization with SFB." (PMID 34566952, 2021). "Although CD3-CD4- cells were the main source of IL-22 single cytokine production in cecum, CD3+CD4+ cells contributed nearly 20% of IL-22 production after Salmonella infection." (PMID 34566952, 2021). "Taken together, these data demonstrate that presence of SFB alone is sufficient for the rapid production of IL-17A and IL-22 by CD4+ T cells after Salmonella infection." (PMID 34566952, 2021). "Predictably, 2W-Salmonella infection induced T cell-intrinsic expression of genes involved in type 1 and type 17 immune responses, including Tbx21 (Tbet), Rorc (RORγt), Il17d/f and Il22." (PMID 34237106, 2021). "Considering that IL-22 exhibits both protective and pathologic effects, the regulatory role of IL-22BP during Salmonella infection is uncertain." (PMID 28770173, 2017). "But meanwhile the regulation of IL-22BP expression is crucial for controlling the activity of IL-22-mediated intestinal tissue damage, especially during later stages of Salmonella infection." (PMID 28770173, 2017). "IL-23 also regulates IL-22 production, but during acute Salmonella infection, there was only a slight decrease in IL-22 production in p19−/− mice, which was not significant but consistent with prior studies." (PMID 22624013, 2012). "The IL-23/IL-22 axis plays a crucial role in innate immunity against Salmonella infection, contributing to protection through various mechanisms such as IL-22-regulated expression of antimicrobial peptides and acute-phase proteins, as well as IL-17A-dependent neutrophil recruitment." (PMID 39767818, 2024). "Indeed, recent research has shown that, under experimental settings, an immune-compromised host (through loss of TLR signaling, IL-22 production, or STAT2 signaling) is better equipped to contain Salmonella infection." (PMID 38236896, 2024). "IL22 may also contribute to Salmonella colonisation and the carrier state in pigs as its production was increased following experimental Salmonella infection." (PMID 35369884, 2022). "Similarly, IL-17 and IL-22 play protective roles in Salmonella infection, and IL-22 can enhance the secretion of antimicrobial peptides in intestinal epithelial cells." (PMID 34068994, 2021).
Salmonella Infections (continued). "Notably, at early stages of Salmonella infection enhanced numbers of CD4+ T cells producing only IL-22 are observed in SFB colonized mice, which to our knowledge is the first report to observe microbiota modulation of Th22 cells in mice." (PMID 34566952, 2021). "Salmonella infection of mice has exposed another reciprocal relationship in which epithelial cells in infected mice make IL-23, which can act on IELs to secrete IL-22; IL-22 promotes anti-microbial peptide synthesis and secretion by epithelial cells, particularly Paneth cells." (PMID 31569537, 2019). "Both IL-17 and IL-22 are produced in the intestinal mucosa early after oral Salmonella infection." (PMID 30216367, 2018). "Thus during acute Salmonella infection IL-22 promotes intestinal inflammation, and a portion of this response is regulated independently of IL-23." (PMID 22624013, 2012). "Systemic and typhoidal mouse models of Salmonella infection indicate that IL-23's function is largely masked by IL-12 and that IL-23 enhances protection against systemic Salmonella infection primarily through IL-22 and to a lesser extent IL-17A." (PMID 22624013, 2012). "The IL-23/IL-22 axis during innate immunity against Salmonella may contribute to protection against Salmonella infection by several ways, such as IL-22-regulated expression of anti-microbial peptides and acute phase proteins and IL-17A-dependent neutrophil recruitment." (PMID 34943999, 2021). "Since Salmonella infection results in a massive cytokine storm in the intestinal mucosa, we hypothesized that infection-induced cytokines would potentially be required to efficiently stimulate IL-22 production from Th22 or related CD4+ cell subpopulations." (PMID 34566952, 2021). "Both wild-type and knockout chickens showed significant upregulation of pro-inflammatory cytokines after Salmonella infection, including IFN-γ, IL-1β, IL-22, LITAF, and the chemokine K203, compared to their mock-infected controls." (PMID 40438105, 2025). "The induction of cytokines and immune relevant proteins such as IL1β, IL6, IL8, IL12, IL17, IL18, IL22, IL23, IFNγ, LITAF or iNOS following Salmonella infection of chickens have been reported repeatedly in many studies." (PMID 25475706, 2014). "FACS analysis of cecal CD4+ T cells after Salmonella infection of eSPF+SFB mice revealed that ~70% of IFN-γ producing CD4 T cells did not secrete IL-17A or IL-22 indicating a classical Th1 phenotype." (PMID 34566952, 2021). "Subsequent studies have reported that IL-22 is not protective in Salmonella infection." (PMID 37483638, 2023). "Moreover, unlike Salmonella infection CD4+ T cells from the SI also released IL-22 upon ex vivo restimulation suggesting that these cells also reside in the SI." (PMID 34566952, 2021). "Besides, they identifiy that SFB induces, in the context of the eSPF microbiota, the acquisition of diverse cytokine-production profiles in CD4+ T cells, including a subset that produces IL-22 but not IL17A after Salmonella infection." (PMID 34566952, 2021). "In absence of IL-22, murine model developed liver necrosis upon Salmonella infection." (PMID 33042126, 2020). "Moreover, we showed that these IL-22+IL-17- T cells, presumably Th22, develop independent of the signals required for classical Th17 differentiation and release these cytokines in the mucosa early during enteric Salmonella infection." (PMID 34566952, 2021). "We characterized the activation and memory state of SFB-induced IL-17A and/or IL-22 producing CD4+ T cells based on the expression of specific markers including CCR6, CD44, and CD62L in the presence or absence of Salmonella infection." (PMID 34566952, 2021). "This does not mean that these cells do not respond to Salmonella infection as IL17, IL22 or IFNγ expressed by T-lymphocytes are induced within the range of 10 to 100 fold." (PMID 25475706, 2014).
Salmonella Infections (continued). "Together, these data suggest that, CD4+ T cells do not express IL-22 in steady state conditions in the intestine and that CD4+ T cells are a source of rapid or “innate-like” IL-22 responses in the cecum mucosa early after Salmonella infection." (PMID 34566952, 2021).
Sepsis (23 papers, 2014 to 2025). Sepsis is defined as life-threatening organ dysfunction caused by a dysregulated host response to infection. "However, further studies are warranted to investigate the underlying mechanisms of IL-33, PGE2, IL-17A, and IL-22 in septicemia." (PMID 33178181, 2020). "In the current study, serum levels of IL-22 were determined in pediatric patients with sepsis, and the potential roles and underlying mechanisms of recombinant mouse IL-22 was investigated in lipopolysaccharide (LPS)-induced acute liver injury (ALI) and cells treated with LPS." (PMID 33177520, 2020). "Both, rodent endotoxemia and sepsis associate with enhanced IL-22 production." (PMID 28706520, 2017). "In addition, by strengthening the crucial parameter of intestinal barrier integrity, local IL-22 is supposed to prevent translocation of pathogenic bacteria that otherwise pose a risk for sepsis development." (PMID 28706520, 2017). "This would suggest that adequate levels of IL-22 must be maintained to optimize immune function, whereas higher levels may induce increased expression of IL-10, enhancing bacterial growth and increasing the risk of sepsis." (PMID 28368347, 2017). "On the other hand, P2X1 significantly suppresses the secretion of the growth-promoting factor interleukin-22 (IL-22) in vitro, thereby impairing the regeneration and repair of damaged hepatocytes during the late stages of sepsis." (PMID 41041630, 2025). "The cytokine profile analysis revealed that ghrelin and Fer-1 effectively normalized the expression of IL-6, IL-1β, TNF-α, and IL-22, which were dysregulated during sepsis, highlighting their anti-inflammatory properties." (PMID 39857660, 2024). "After more experimental validations, this result can help design future clinical trials to treat organ dysfunctions with IL-22 for pediatric sepsis." (PMID 37395630, 2022). "Similar to our finding, in an acute polymicrobial sepsis model, IL-22 blockade by IL-22BP-Fc was also shown to be protective against bacteria spread and organ failure." (PMID 34992594, 2021). "In the current study, we demonstrate for the first time that IL-33 plays a role in regulating the production of PGE2, IL-17A, and IL-22 in septicemia." (PMID 33178181, 2020). "Inhibition of PGE2, IL-17A, and IL-22 facilitated the development of septicemia and organ damage in S. epidermidis-infected mice, as well as reducing their survival." (PMID 33178181, 2020). "IL-22, the other major immunomodulatory secretory product of Th-17 cells, has also been shown to negatively affect outcomes during sepsis." (PMID 28368347, 2017). "Since local IL-22 is crucial for maintenance of intestinal barrier function and sepsis pathogenesis, colonic IL-22 expression was determined and found likewise upregulated upon cold stress." (PMID 28706520, 2017). "As sepsis progressed in polymicrobial peritonitis, activation of IL-22RA1 and induction of IL-22 produced a pro-inflammatory response that exacerbated the infection." (PMID 26793707, 2015). "Bacterial spread and organ failure, which are consequences of polymicrobial peritonitis, appeared to increase due to the role of IL-22 in the progression of sepsis." (PMID 26793707, 2015). "They found that both IL-22 and IL-10 were expressed in the presence of sepsis as a consequence of polymicrobial peritonitis." (PMID 26793707, 2015). "Another cytokine which has been studied and seems to be really involved in the pathogenesis of sepsis is IL-22." (PMID 25614712, 2014). "Treatment of mice with IL-22 pb before sepsis led to increased accumulation of neutrophils and mononuclear phagocytes, as well as a reduction in bacterial burden at the site of infection." (PMID 25614712, 2014). "In a small group of hospitals within a single health center, IL-22 levels were slightly increased in the serum of patients with sepsis." (PMID 25614712, 2014).